FOXC1 (forkhead box C1)
Diseases named in the same sentence as FOXC1 in open-access papers (continued):
Sharing a sentence is not in itself a finding about the gene and the disease.
breast carcinoma (continued). "In breast cancer, circIRAK3 sponged miR-3607 to regulate the expression of forkhead box C1 and further mediated breast cancer cell migration." (PMID 32368305, 2020). "Lower levels of FOXC1 promoter methylation correlated with increased mRNA expression and inferior overall survival in one study which encompassed various subtypes of breast cancer." (PMID 30764547, 2019). "In analyses of large datasets of breast cancer patient gene expression, FOXC1 expression correlated positively with increasing activation of an Hh gene signature and lower disease-free survival." (PMID 30764547, 2019). "For instance, overexpression of FOXC1 in breast cancer cells increased the proportion of cells expressing the putative stem cell markers ALDH and CD133, and enhanced mammosphere formation in vitro." (PMID 30764547, 2019). "In this context, TGF-β-mediated repression of FOXC1 reduced transcription of the pro-apoptotic mediator Bim, enhancing breast cancer cell survival." (PMID 30764547, 2019). "In the context of BLBC, FOXC1 knockdown in various breast cancer cell lines suppressed proliferation and induced more differentiated cellular morphology." (PMID 30764547, 2019). "Conversely, forced expression of FOXC1 in MCF-7 breast cancer cells significantly enhanced their proliferation and anchorage-independent growth in vitro." (PMID 30764547, 2019). "FOXC1 expression also appears to be deregulated by aberrant promoter demethylation in the context of breast cancer." (PMID 30764547, 2019). "In another study, forced expression of FOXC1 in a panel of breast cancer cell lines was accompanied by an increase in levels of cyclin D1 and c-Myc." (PMID 30764547, 2019). "Crucially, forced expression of FOXC1 rendered breast cancer cells resistant to pharmacologic inhibition of Smoothened, a membrane-bound receptor involved in canonical Hedgehog signaling." (PMID 30764547, 2019). "To confirm the subtype-specific anti-metastatic capacity of FOXC1, we exogenously expressed FOXC1 in two different Luminal B human breast cancer cell lines and assayed invasiveness via a Boyden chamber assay." (PMID 29959321, 2018). "Ectopic FOXC1 expression promoted cell migration, invasion and proliferation, whereas knockdown of FOXC1 expression induced opposite effects in breast cancer cells." (PMID 29552326, 2018). "To establish the prognostic importance of the FOXC1 gene signature, we revisited KM plotter to analyse the effect of the FOXC1 signature levels across different breast cancer subtypes." (PMID 29959321, 2018). "Our results confirmed the role of EZH2 in regulation of FOXA1 and FOXC1 expression in breast cancer cells but the effect of EZH2 depletion on these genes expression was cell- dependent." (PMID 29864144, 2018). "This observed mutual exclusivity supported the mechanism of EZH2-mediated FOXC1 repression in Luminal B breast cancer." (PMID 29959321, 2018). "In this study, we identify a mechanism through which EZH2 mediates repression of FOXC1 to promote metastasis in Luminal B breast cancer." (PMID 29959321, 2018). "Here, the authors demonstrate that targeting epigenetic modifier Ezh2 hinders metastatic behaviour in Luminal B breast cancer models, and highlight a mechanism where Ezh2 contributes to metastatic behaviour by repression of FOXC1." (PMID 29959321, 2018). "In this study, we determined the impact of OGT on expression of EZH2 target genes FOXA1 and FOXC1, that are involved in breast cancer progression." (PMID 29864144, 2018). "To interrogate further correlations between FOXC1, EZH2 and downstream FOXC1 targets at the protein level in human breast cancer, we made use of recently published proteomic analysis of a subset of TCGA breast cancer patients." (PMID 29959321, 2018). "Expression of FOXC1 was correlated with Gli2 expression and its downstream targets in breast cancers." (PMID 29552326, 2018). "Expression of FOXC1 was significantly correlated with that of Gli2 and its downstream targets in breast cancers." (PMID 29552326, 2018).
breast carcinoma (continued). "Although the studies of FOXC1 in basal-like breast cancer and hepatocellular carcinoma are well underway, the investigation of FOXC1 in endometrial cancer has just begun." (PMID 29487724, 2018). "Other studies have followed suit, demonstrating that FOXC1 is not only a major player in this breast cancer subtype, but also in hepatocellular carcinoma (HCC), endometrial cancer, Hodgkin's lymphoma (HL), and non-Hodgkin's lymphoma (NHL)." (PMID 29487724, 2018). "FOXC1 is expressed not only in breast cancer subtypes such as basal-like breast cancer (BLBC), but also in hepatocellular carcinoma (HCC), endometrial cancer, Hodgkin’s lymphoma (HL), and non-Hodgkin’s lymphoma (NHL)." (PMID 30564302, 2018). "To explore this, we first analysed EZH2 and FOXC1 transcript levels in a large cohort of breast cancer patient data from The Cancer Genome Atlas (TCGA) database." (PMID 29959321, 2018). "FOXC1 promoted progress of many cancers, such as breast cancer (especially basal-like breast cancer), hepatocellular carcinoma, gastric cancer and so on." (PMID 29552326, 2018). "FOXC1 also promotes proliferation, migration, invasion and drug resistance in hepatocellular carcinoma and breast cancer." (PMID 30189871, 2018). "FOXC1 is involved in many cancers such as breast cancer, liver cancer, Hodgkin’s and non-Hodgkin’s lymphoma, pancreatic cancer, and endometrial cancer." (PMID 30360388, 2018). "More recently, the dominant roles of FOXC1, especially in basal-like breast cancer, have been revealed and discussed thoroughly." (PMID 30360388, 2018). "Having established that FOXC1 can drive an anti-metastatic program, we sought to confirm the relevance of this finding in a clinical context using both publicly available breast cancer patient data sets and human patient specimens." (PMID 29959321, 2018). "Taken together, these data provide compelling evidence that pharmacological intervention targeting the EZH2-dependent repression of a FOXC1-driven transcriptional program can hinder the metastatic properties of human Luminal B breast cancer." (PMID 29959321, 2018). "In recent years, rapidly accumulating evidence implicates forkhead box C1 (FOXC1) in cancer, especially in studies of basal-like breast cancer (BLBC)." (PMID 29487724, 2018). "Previously, it has been shown that ectopic overexpression of FOXC1 in breast cancer cell lines induces aggressive phenotypes." (PMID 28493031, 2017). "Another study indicated that FOXC1 demethylation, which results in its overexpression, is closely correlated with chemoresistance in locally advanced breast cancer patients receiving neoadjuvant anthracycline treatment." (PMID 28493031, 2017). "Conversely, shRNA knockdown of FOXC1 in breast cancer cell lines with high endogenous levels of FOXC1 led to opposing effects with the loss of aggressive phenotypic features." (PMID 28493031, 2017). "Additional research regarding the mechanism of how FOXC1 affects chemotherapeutic efficacy and FOXC1 is warranted to supply further evidence in selecting appropriate chemotherapeutics for breast cancer patients in clinical settings." (PMID 28493031, 2017). "Many studies showed that FOXC1 was related with breast cancer, liver cancer, lung cancer, stomach cancer and pancreas cancer." (PMID 27533251, 2016). "A representative example of this group is FOXC1, an important regulator of Basal-like breast cancer and a repressor of GATA3." (PMID 27539783, 2016). "Forkhead box C1 (FOXC1) has been identified as a specific marker expressed in BLBC in general breast cancer cohorts." (PMID 27708239, 2016). "The transcription factor FOXC1, an important biomarker of basal-like breast cancer, is a member of the anti-GATA3 group and is anticorrelated with GATA3 expression in TCGA data (Pearson's r = −0.602)." (PMID 27539783, 2016).
breast carcinoma (continued). "Our earlier studies showed that FOXC1 is a potential biomarker for basal-like breast cancer (BLBC), and its overexpression correlates with poor overall survival in breast cancer." (PMID 27533251, 2016). "FOXC1 interacts with the Bmp-responsive enhancer to reduce Msx2 expression and contribute to skull vault growth in breast cancer." (PMID 26198045, 2016). "Our previous studies showed FOXC1 increases expression of Cyclin D1, phosph-P65 and P65 in breast cancer cells." (PMID 27533251, 2016). "We examined an institutional cohort of breast cancer patients with germline BRCA1 (n=46) and BRCA2 (n=35) mutations and found that FOXC1 expression on immunohistochemical staining is associated with BRCA1 vs BRCA2 mutations [30/46 vs. 6/35]." (PMID 27708239, 2016). "It has been shown by others that FOXC1 acts as a complex regulator in breast cancer, as both inhibiting and enhancing proliferative effects were observed after FOXC1 up-regulation." (PMID 25875420, 2015). "Many individual markers such as stem cell marker Bmi-1, lysyl oxidase-like 2 (LOXL2), FOXC1, α9β1 integrin, and monocarboxylate transporter 1 were studied to find specific markers for basal-like breast carcinoma." (PMID 25510449, 2014). "Several recent studies have reported that FOXC1 overexpression is strongly correlated with poor survival in the patients of multiple cancers such as breast cancer, pancreatic ductal adenocarcinoma, non-small cell lung cancer, or hepatocellular carcinoma." (PMID 24889262, 2014). "FOXC1 has also been reported to promote the invasiveness of breast cancer cells by inducing the expression of matrix metalloprotease 7 an enzyme known to be able to degrade components of the ECM." (PMID 23907184, 2013). "Foxc1, downstream of TGFβ signaling, is important for growth suppression in several human cancer cell lines, however, there is growing evidence that high expression of Foxc1 is correlated with increased breast cancer growth." (PMID 23862012, 2013). "FOXC1 overexpression is a consistent feature in basal-like breast cancer compared to other breast cancer subtypes, and is indicative of poor overall survival in patients with basal-like breast cancer." (PMID 23620774, 2013). "All three are targets of inactivation in breast cancer and both FOXC1 and FOXF1 are subjected to promoter methylation." (PMID 23324568, 2013). "Low FOXC1 gene expression in both methylated and unmethylated DCIS and IDCs indicates that the loss of its expression is an early event during breast cancer progression." (PMID 20056007, 2010). "The other chromosomal regions harbouring the genes with a high correlation to FOXC1 methylation have all been reported to either have gain or losses in breast cancer." (PMID 20056007, 2010). "The tumours with less methylation and somewhat higher expression of FOXC1 tended to be of the basal-like and normal-like breast cancer subtypes, as determined by gene expression profiling." (PMID 20056007, 2010). "However, unlike FOXA1, this indirect down-regulation of ER level, caused by competition between FOXC1 and GATA3, cannot inhibit the progression of breast cancer." (PMID 40003882, 2025). "The role of FOXC1 in the development and metastasis of breast cancer has been widely studied." (PMID 40003882, 2025). "Although it is objectively recognized that FOXC1 plays a dual role in breast cancer, in actuality, its function in augmenting the invasiveness of breast cancer—particularly in triple-negative breast cancer (TNBC) and basal-like breast cancer (BLBC)—has been more extensively researched." (PMID 40003882, 2025). "In addition, PcG proteins mediate the elevation of FOXC1 expression via H3/H4 acetylation of the FOXC1 promoter in breast cancer." (PMID 40703976, 2025).
breast carcinoma (continued). "In the gene regulatory network by using the NetworkAnalyst web server, we found five (two from Encode and three from Jasper such as FOXC1, GATA2, FOXL1, ZNF24 and NR2F6) potential Transcription Factors (TFs) and all of those are linked with several cancer including breast cancer." (PMID 38717954, 2024). "In breast cancer, FOXC1 activates the transcription of FGFR1 to enhance the EMT progression." (PMID 39093497, 2024). "Notably, increased FOXC1 expression has been shown to promote cell proliferation in several cancer cell types, including breast cancer, cervical cancer, and gastric cancer." (PMID 39450403, 2024). "Since TNBC is a heterogeneously classified subgroup of breast cancer, the identification of core conserved FOXC1-regulated gene networks will elucidate the functional role of FOXC1 in TNBC and could improve our understanding of TNBC pathogenesis." (PMID 39171293, 2024). "The core gene targets of FOXC1 identified in this study form a conserved list of genes important in breast cancer, a molecular signature for FOXC1-overexpressing cancers and could present as attractive targets for subtype-independent breast cancer therapies." (PMID 39171293, 2024). "We analyzed whether FOXC1 binds and regulates similar targets in TNBC as those regulated by the ERα-associated TFs in luminal breast cancer." (PMID 39171293, 2024). "Furthermore, it has been reported that the expression of FOXC1 is increased in various types of cancer, including breast cancer, hepatocellular carcinoma, pancreatic and non-small cell lung cancers, and colon cancer and associated with cancer progression." (PMID 35365611, 2022). "Pertinent to this review, RAS/MAPK pathway was demonstrated to regulate FOXC1 expression in breast cancer, suggesting that targeted inhibition of this pathway may offer therapeutic benefit in FOXC1+ pro-metastatic cancers." (PMID 34540690, 2021). "And in the study of DZNep’s role on mice airway smooth muscle cells and human basal-like breast cancer cells, the NF-κB nuclear translocation was promoted via the IκB phosphorylation, which credited to the upregulated transcription of Foxc1 after the inhibition of EZH2 and subsequent H3K27me3." (PMID 34930462, 2021). "In breast cancer, Cui and colleagues demonstrated that ectopic FOXC1 expression in ERα-positive MCF7 luminal breast cancer cells greatly diminished the effects of growth-stimulatory B-estradiol and growth-inhibitory antiestrogen treatment with Tamoxifen and Fulvestrant." (PMID 34540690, 2021). "Thus, after breast cancer, clinical assessment of FOXC1 expression status for prognostic stratification of patients is most likely to be useful in colon cancer." (PMID 34540690, 2021). "Similarly, an analysis of breast cancer samples from the TCGA database and Curtis dataset also revealed a strong correlation between FOXC1 and GLI2." (PMID 34572373, 2021). "Repressive complexes may be recruited by negative regulators such as FOXC1 or other repressors, including the transcription factor ELF5, shown to repress ESR1 and a set of ERα-associated genes with promotion of basal-like breast cancer characteristics." (PMID 34831189, 2021). "FGFR1 is a proven transcriptional target of FOXC1 in breast cancer." (PMID 34540690, 2021). "Previous reports by us and others had shown that FOXC1 expression could accurately identify patients with the basal-like breast cancer (BLBC) molecular subtype, the most aggressive subtype of breast cancer." (PMID 34540690, 2021). "Indeed, forced expression of wild-type BRCA1 in breast cancer cell lines silenced FOXC1, whereas GATA3 knockdown induced its expression." (PMID 30764547, 2019). "Indeed, studies of breast cancer cells found that forced expression of FOXC1 induced transcription of MMP7, or MMP2 and MMP9." (PMID 30764547, 2019). "Interestingly, a role for TGF-β signaling in maintaining repression of FOXC1 was identified in one study of breast cancer cells." (PMID 30764547, 2019).
breast carcinoma (continued). "This could reflect the occurrence of different mechanisms of silencing FOXC1 across breast cancer subtypes." (PMID 29959321, 2018). "Moreover, the ectopic overexpression of FOXC1 invoked more aggressive breast cancer phenotypes, including epithelial-mesenchymal transition, increased cell proliferation, increased migration, and increased invasion." (PMID 29487724, 2018). "FOXC1 activates Notch pathway by directly regulating Dll4 in endothelial cells and enhances Hedgehog signaling activity via Gli2 binding in basal-like breast cancer." (PMID 30189871, 2018). "The Forkhead box C1 (FOXC1) transcription factor promotes CSC properties in basal-like breast cancer, which could activate Smo-independent Hh signalling and Gli2, and provides novel insight into anti-Hh therapy resistance in cancer progression." (PMID 29899399, 2018). "Like EZH2, we found that FOXC1 functions in a context-specific manner in breast cancer." (PMID 29959321, 2018). "Combination of FOXC1 expression with matrix metalloprotease 7 (MMP7) expression can be used as an independent predictor of patient outcome in multivariate analyses of two breast cancer patient cohorts." (PMID 29552326, 2018). "Conversely, we also confirmed that FOXC1 depletion could rescue reduced invasiveness mediated by administration of GSK-126 in two separate human Luminal B breast cancer cell lines in vitro." (PMID 29959321, 2018). "Therefore, the function of FOXC1 in breast cancer, specifically BLBC, has been extensively investigated." (PMID 30564302, 2018). "Expression of FOXC1 was dramatically correlated with expression of EGFR in human breast cancers." (PMID 29552326, 2018). "FOXC1 was firstly reported to be overexpressed in basal-like breast cancer (BLBC) by our group." (PMID 29552326, 2018). "In light of its emerging role in normal development and breast cancer tumorigenesis, the present study was designed to explore whether FOXC1 transgene expression affects mammary gland development in vivo." (PMID 29070831, 2017). "In addition, it was shown that overexpression of FOXC1 increased the tumorigenic properties of breast cancer cells." (PMID 28028927, 2017). "Expression of FOXC1 was increased with progress of breast cancer." (PMID 28028927, 2017). "In summary, FOXC1 increased the tumorigenic properties of breast cancer cell lines." (PMID 28028927, 2017). "Moreover, EGF-induced FOXC1 expression occurs not only in breast cancer cells but also in prostate cancer cells." (PMID 28629477, 2017). "Our results suggest that FOXC1 may serve as a readout of EGF-NF-κB signaling activity in breast cancer." (PMID 28629477, 2017). "FOXC1, a member of Forkhead box transcription factors essential for mesoderm tissue development in vertebrates 28, 29, consistently showed the highest correlation with the basal‐like subtype compared to other subtypes in the breast cancer." (PMID 28028927, 2017). "In summary, our study has firstly reported significant correlation between FOXC1 and ERα in breast cancer, which might be responsible for the poor progress of triple‐negative breast cancer in clinic." (PMID 28028927, 2017). "FOXC1 expression was increased as development of breast cancer." (PMID 28028927, 2017). "Although FOXC1 over-expression is found in some types of breast cancer cells, liver cancer cells, acute myeloid leukemia, and increased FOXC1 in these cancer cells is associated with proliferation, there is no study reported FOXC1 over-expression in keratinocyte-derived cancer." (PMID 27907090, 2016). "Combined, these results suggest that FOXC1 is essential for BRCA1-mutant breast cancer cell growth and may predict sensitivity to treatment with olaparib in BRCA1-mutant cells, which warrants further validation using clinical samples." (PMID 27708239, 2016).